MUC5B (mucin 5B, oligomeric mucus/gel-forming)
Diseases named in the same sentence as MUC5B in open-access papers (continued):
Sharing a sentence is not in itself a finding about the gene and the disease.
lung adenocarcinoma (continued). "To explore the downstream molecular effects of MUC5B, we performed RNA-seq analysis comparing lung adenocarcinoma cells with and without MUC5B knockout." (PMID 41409294, 2025). "We used siRNA targeting MUC5B (siMUC5B) and a negative control siRNA (siNC) to transfect both A549 and H1975 lung adenocarcinoma cells." (PMID 41409294, 2025).
xerostomia (10 papers, 2012 to 2025). Dryness of the mouth resulting from reduced salivary secretion. "Low levels of muc5b expression are highly correlated with xerostomia, and vaping is associated with this anomaly, thereby establishing a correlation between vaping and xerostomia at the molecular level." (PMID 39996934, 2025). "In patients with pSS, the development of xerostomia has been linked to hypo-sulphation and hypo-glycosylation of MUC5b reducing the water-retaining capacity of MUC5b." (PMID 33661446, 2021). "Furthermore, we proposed that a dry mouth sensation in xerostomia patients might be linked to the lower availability of saliva in the oral cavity and lower MUC5b output." (PMID 33661446, 2021). "Following transplantation of collagen-based hSGOs into a mouse model of xerostomia, we observed successful integration of the organoids into host tissues, leading to the differentiation of ductal cells and MUC5B-producing acinar cells." (PMID 39183328, 2024). "MUC5B plays a crucial role in lubricating the oral mucosa and its levels are significantly diminished in patients with xerostomia." (PMID 39183328, 2024). "A reduced level of sulfation of MUC5B has been reported in patients with xerostomia due to Sjögren’s syndrome." (PMID 34627217, 2021). "This pilot study showed a trend towards lower MUC5B levels in the SMG saliva of patients with severe xerostomia 12 months after RT for HNC." (PMID 22704532, 2012). "Furthermore, it is assumed that after radiotherapy, MUC5B levels vary depending on the xerostomia level." (PMID 33572065, 2021). "The multivariate regression analysis and the insignificant correlation between chewing-stimulated salivary flow rate and the Xerostomia Inventory score in dry mouth patients show that other factors, e.g. MUC5b output, will play a more important role in explaining the dry mouth sensation." (PMID 33661446, 2021). "The authors did not observe a link between the parameters analyzed (salivary amylase activity, MUC5B concentrations, or the ratios of amylase:MUC5B) in either stimulated or unstimulated saliva or in the xerostomia inventory score or intestinal disease activity." (PMID 33202858, 2020). "Qualitative saliva parameters like MUC5B need further investigation in RT-induced xerostomia." (PMID 22704532, 2012). "Our hypothesis in this pilot study was that MUC5B levels, as a qualitative parameter in human saliva, could better explain xerostomia compared to quantitative saliva measurements in RT patients." (PMID 22704532, 2012). "Therefore, we suggest that hSGOs expressing MUC5B may improve salivary composition in xerostomia models." (PMID 39183328, 2024). "Therefore, dry mouth sensation of xerostomia patients might be explained by lower availability of saliva in the oral cavity leading to lower MUC5b and proteins in the mucosal salivary film." (PMID 33661446, 2021). "In non-radiation-induced patients who suffered from dry mouth (e.g., Sjögren syndrome), it was found that MUC5B was still present on the inner lining despite a zero flow rate." (PMID 33572065, 2021). "At 12 months, the median MUC5B was higher in patients with no or mild xerostomia compared to patients with severe complaints, although the difference was not statistically different at the 0.05 level." (PMID 22704532, 2012). "Apart from the free MUC5B fraction measured in SMG saliva in this study, there may be other mucin-related factors that can explain xerostomia." (PMID 22704532, 2012). "MUC5B levels in submandibular gland saliva have showed a tendency to be higher among head and neck cancer patients who report no or mild xerostomia 12 months post treatment compared with patients with severe xerostomia who showed almost undetectable levels of MUC5B." (PMID 34627217, 2021). "Almost half of the patients with severe xerostomia had no detectable MUC5B at 12 months after RT." (PMID 22704532, 2012). "Half of the patients with severe xerostomia had no detectable MUC5B at 12 months after RT." (PMID 22704532, 2012).
mucinous adenocarcinoma (9 papers, 2013 to 2024). An invasive adenocarcinoma composed of malignant glandular cells which contain intracytoplasmic mucin. "In addition, MUC5B, which is involved in goblet cell mucus production, is down-regulated in mucinous adenocarcinoma, and was previously shown to be associated with LUAD cancer-specific DNA methylation changes." (PMID 37742993, 2023). "A few recent studies have shown that MUC5B is also frequently expressed in lung mucinous adenocarcinoma, and the expression of MUC5B is inversely correlated with the differentiation of the tumor." (PMID 24176033, 2013). "To validate this result, we performed immunofluorescence on both mucinous adenocarcinoma (n = 3) and UIP specimens (n = 4) for MUC5B, MUC5AC, and BPIFB1." (PMID 37005656, 2023). "A gene signature of invasive mucinous adenocarcinoma of the lung, which includes transcription factors (FOXA3, SPDEF, and HNF4A) and mucin proteins (MUC5AC, MUC5B, and MUC3) has been identified." (PMID 36860703, 2022). "Adenocarcinomas in FOXM1 transgenic mice expressed increased MUC5B and MUC5AC, and reduced NKX2.1, which are characteristics of mucinous adenocarcinomas." (PMID 29267283, 2017). "Additionally, markers of invasive mucinous adenocarcinoma (MUC5AC, MUC5B, SPDEF, FOXA3) were highly expressed in organoids, retaining the histological characteristics of the patient’s original tumor." (PMID 37508518, 2023). "Thus, a distinguishing factor for fibrotic/UIP mucus is the high abundance of MUC5B and BPIFB1, whereas MUC5AC is predominant in mucinous adenocarcinoma mucus." (PMID 37005656, 2023). "Inversely, mucinous adenocarcinoma mucus was positive for MUC5AC, whereas MUC5B and BPIFB1 are largely negative at the immunofluorescence level (white arrows point where MUC5B/BPIFB1 are absent)." (PMID 37005656, 2023).
hypersensitivity pneumonitis (8 papers, 2021 to 2025). Hypersensitivity pneumonitis (HP) is a pulmonary disease with symptoms of dyspnea and cough resulting from the inhalation of an antigen to which the subject has been previously sensitized. "A MUC5B–TOLLIP haplotype was associated with reduced survival in fibrotic hypersensitivity pneumonitis (HR 6.92, p = 0.006), while in IPF, another MUC5B–TOLLIP haplotype appeared to be protective (HR 0.37, p = 0.009)." (PMID 40475958, 2025). "In hypersensitivity pneumonitis patients, the T allele of the MUC5B gene predicts lower baseline FVC and its subsequent decrease." (PMID 37686350, 2023). "MUC5B, TERC and IVD remained statistically significant after including all variants in a single model of fibrotic hypersensitivity pneumonitis." (PMID 37410458, 2023).
dental caries (7 papers, 2018 to 2025). The decay of a tooth, in which it becomes softened, discolored, and/or porous. "MUC5B prevents Streptococcus mutans, one of many bacteria capable of causing dental caries, from attaching to surfaces, suggesting a role for MUC5B in limiting tooth decay." (PMID 35782137, 2022). "The MUC5B gene rs2735733, rs2249073, and rs2857476 were associated with dental caries; all the three variants were present in 30.09, 25.24, and 27.18%, respectively, of individuals from our cohort, indicating that Indians are highly susceptible to dental caries." (PMID 33101356, 2020). "Previously, MUC5B was found to elicit synergistic effects in early biofilms of oral colonizers S. gordonii and A. naeslundii that seemed to promote attachment, while downregulating dysbiotic activities related to dental caries development." (PMID 40008185, 2025). "Salivary mucin MUC5B has been suggested to support eubiosis in early oral biofilms by regulating the attachment of commensals, while downregulating dysbiotic activities related to dental caries development, such as microbial carbohydrate transport and metabolism." (PMID 40008185, 2025). "Several previous studies have identified an association between several genes and dental caries, including genes related to enamel formation such as AMBN, AMELX, and ENAM; taste receptor genes such as TAS2R38, TAS1R2; immune-related genes such as HLA; and saliva genes such as MUC5B, PRH1." (PMID 38414691, 2024).
Sjögren syndrome (7 papers, 2012 to 2025). "Loss of MUC5B sulfation was observed in the mucous acini from labial salivary glands of patients with Sjögren syndrome and was unrelated to alterations in saliva quantity." (PMID 22704532, 2012). "In previous studies of Sjögren's syndrome, a chronic autoimmune disease in which the body’s white blood cells destroy the exocrine glands, a relationship between MUC5B, von Willebrand factor and diabetes was suggested, indicating a potential role of MUC5B in cardiovascular complications of T2D." (PMID 28346466, 2017). "Key words:Primary Sjögren's syndrome, mucin, MUC7, MUC5B, MUC1, sulphate oligosaccharides." (PMID 33247578, 2021). "It is a common opinion that Primary Sjögren Syndrome (pSS) damages the exocrine glands and determines the reduction of secreted saliva, some studies show that there are qualitative anomalies of the mucins produced in saliva, including MUC7, MUC5B, MUC1." (PMID 33247578, 2021).
chronic bronchitis (6 papers, 2013 to 2024). A type of chronic obstructive pulmonary disease characterized by chronic inflammation in the bronchial tree that results in edema, mucus production, obstruction, and reduced airflow to and from the lung alveoli. "Collectively, the current study indicates that high MUC5AC expression and low MUC5B expression in goblet cells in the large airways are associated with cigarette smoke exposure and with chronic bronchitis and emphysema." (PMID 39769414, 2024). "Chronic Bronchitis (CB): Following the analyses of sputum mucin concentration data, we tested for an association between the lead variant for sputum MUC5B concentration (rs140324259) and CB in the larger SPIROMICS population (N = 1257)." (PMID 37352370, 2023). "Wood smoke exposure resulted in increased expression of MUC1, MUC5AC, and MUC5B in the chronic bronchitis-like bronchial model." (PMID 38245732, 2024). "In our cohort, smoking exposure, chronic bronchitis, and emphysema were associated with high MUC5AC expression but with low MUC5B expression in goblet cells of the large airway mucosa." (PMID 39769414, 2024). "In line with this, in our cohort, high MUC5AC and low MUC5B expression were associated with smoking exposure as well as with unfavorable traits of COPD, such as chronic bronchitis and emphysema." (PMID 39769414, 2024). "The strongest association we detected, for MUC5B on chromosome 11, was also associated with features of COPD, including chronic bronchitis and acute exacerbations, in one COPD study population but not another." (PMID 37352370, 2023). "The hyper-concentration of mucus positively correlates with exacerbation frequencies and has been proposed as a disease driver in chronic bronchitis with MUC5B remaining the predominant mucin at all levels of disease severity." (PMID 34098956, 2021). "Similarly, chronic bronchitis, which is recognized as an unfavorable clinical trait of COPD, was associated with lower MUC5B expression, higher MUC5AC expression, and higher MUC5AC concentration in BW." (PMID 39769414, 2024). "Chronic bronchitis, emphysema, and the progression of chronic airflow limitation during a median follow-up time of 8.4 years were associated with higher MUC5AC and lower MUC5B expression in goblet cells." (PMID 39769414, 2024). "Moreover, the sputum MUC5AC and MUC5B concentrations were associated with common genetic variants, and the top locus for MUC5B might influence COPD phenotypes, in particular chronic bronchitis." (PMID 39769414, 2024). "Patients with chronic bronchitis had higher immunohistochemical MUC5AC expression, higher MUC5AC concentration in BW, and lower immunohistochemical MUC5B expression in goblet cells, as compared with patients without chronic bronchitis at baseline." (PMID 39769414, 2024).
colon cancer (6 papers, 2020 to 2025). "In vitro, down-regulation of MUC5B in gastric cancer and colonic cancer cells leads to a decrease in proliferation, migration, and invasion properties." (PMID 36831639, 2023).
gastric cancer (6 papers, 2020 to 2025). A primary or metastatic malignant neoplasm involving the stomach. "In addition, MUC5B expression has been positively correlated with the poor prognoses of gastric carcinomas." (PMID 32825724, 2020).
pancreatic cancer (6 papers, 2004 to 2025). "A regulatory linkage between dual-specificity phosphatase 28 (DUSP28) and MUC5B/MUC16 was reported in pancreatic cancer cells by a study to elucidate the underlying mechanism by which DUSP28 promotes the development of pancreatic cancer." (PMID 32695780, 2020). "In BxPC3, the presence of several types of mucins (MUC5AC, MUC5B, and MUC16) reflected what is described for pancreatic tumors, which are known to overexpress these proteins." (PMID 32886718, 2020). "The apomucins MUC1, MUC5B, MUC5AC, and MUC6 are expressed in the normal pancreas; MUC1, MUC2, and MUC4 are upregulated in pancreatic tumours, whereas MUC5B, MUC5AC, and MUC6 are slightly downregulated." (PMID 14760381, 2004). "Similarly, MUC5B, more abundant in bile from PDAC patients, has been described to contribute to the survival and migration of pancreatic cancer cells." (PMID 32575903, 2020). "Genetic and/or epigenetic analysis of the upstream enhancer regions in breast and pancreatic cancers, which were functionally validated in this study, may lead to the understanding of the mechanism by which MUC5AC and/or MUC5B is induced in those cancers." (PMID 28255028, 2017).
sarcoidosis (6 papers, 2014 to 2025). Sarcoidosis is a multisystemic disorder of unknown cause characterized by the formation of immune granulomas in involved organs. "The MUC5B variant is also not considered a risk factor in ASSD, myositis, or sarcoidosis; however, the MUC5B rs35705950 promoter variant appears to be associated with asbestosis, potentially due to the fact that asbestosis shares radiological and pathological UIP features with IPF." (PMID 39768847, 2024).
chronic rhinosinusitis (5 papers, 2020 to 2025). Chronic form of sinusitis. "MUC5B was found to be upregulated in patients with chronic rhinosinusitis and associated with a higher prevalence of bacterial biofilms indicating a possible mechanism for bacterial pathogenesis." (PMID 40572318, 2025). "Next, we sought to determine the expression levels of the MUC5AC and MUC5B genes in all patient samples because the respective mucins secreted by nasal epithelial cells have been implicated in chronic rhinosinusitis pathology." (PMID 36902594, 2023). "Muc5AC and MUC5B are types of mucin, and an increase in mucin in the upper airway is associated with upper airway inflammatory diseases such as allergic rhinitis and chronic rhinosinusitis." (PMID 32580467, 2020). "In conclusion, as part of this study we performed bacterial biofilm status evaluation and MUC5AC and MUC5B gene expression quantification in both control and chronic rhinosinusitis patient samples in order to shed light on the possible link between these factors and CRS pathogenesis." (PMID 36902594, 2023).
cyst (5 papers, 2020 to 2025). A sac-like closed membranous structure that may be empty or contain fluid or amorphous material. "However, following bleomycin injury, Muc5b overexpression resulted in enhanced collagen deposition, honeycomb cyst formation, and mucus production, suggesting that a second injury is needed to initiate the fibroproliferative response." (PMID 40526433, 2025). "Interestingly, none of the 187 significantly changed IPF honeycomb cyst proteins were regulated by the MUC5B promoter variant." (PMID 40526433, 2025). "The previous data showed that the overexpressed MUC5B is located in the epithelia cells from honeycomb cysts zone in the IPF lungs, and the ectopic expression of MUC5B may enhance the honeycomb-like cyst formation." (PMID 35111363, 2022).
idiopathic interstitial pneumonia (5 papers, 2012 to 2023). A class of diffuse lung diseases that typically affect the pulmonary interstitium, although some also have a component affecting the airways (for instance, Cryptogenic organizing pneumonitis). "The telomerase gene TERT, the mucin gene MUC5B, and telomeres have all been linked to idiopathic interstitial pneumonias (IIPs) in genome-wide association studies (GWAS)." (PMID 38203718, 2023). "IPF GWAS performed in Japanese and European individuals have identified genetic risk loci within TERT, TOLLIP/MUC5B, and SPPL2C; a GWAS of the broader phenotype idiopathic interstitial pneumonia identified an association within the MUC5B promoter that was also associated with IPF." (PMID 28774304, 2017). "Significant overexpression of the secreted Mucin 5B (Muc5B) protein has been found in IPF lungs and it is hypothesised that excess Muc5B impairs the mucosal host defence; in turn, this may interfere with alveolar repair and leads to the development of idiopathic interstitial pneumonia." (PMID 30704051, 2019).
Allergy (4 papers, 2017 to 2025). An allergy is an immune response or reaction to substances that are usually not harmful. "Expressions of mucin genes implicated in allergy, Muc5ac and Muc5b, were elevated and followed a similar trend to GC numbers." (PMID 29511677, 2018). "MUC5B is the primary mucin responsible for routine mucociliary clearance, whereas MUC5AC is induced during infection and uniquely underlies airway hyperreactivity in allergy." (PMID 40035770, 2025). "Based on their association with allergy and the protein fold change (more than 1.1 or less than 0.9) between ATI responders and non-responders, four potential genes (MUC5B, LBP, C4BPB, LTA4H) were identified as potential biomarkers that indicate an effective AIT." (PMID 33329520, 2020).
colorectal cancer (4 papers, 2020 to 2023). A primary or metastatic malignant neoplasm that affects the colon or rectum. "However, research focused on the MUC5B gene in colorectal carcinomas is limited." (PMID 32695780, 2020).
emphysema (4 papers, 2022 to 2024). "Emphysema and bronchial wall thickening on CT at a follow-up visit were associated with lower MUC5B expression at baseline." (PMID 39769414, 2024). "The MAF of the MUC5B variant was higher in ILD (17.6%) compared to COPD/emphysema (9.3%), CF/BRECT (7.5%), and PHT (7.4%) (p < 0.001)." (PMID 35651878, 2022). "Also, the signs of emphysema at the follow-up visit were associated with lower MUC5B expression, higher MUC5AC expression, and higher MUC5AC concentration in BW at baseline." (PMID 39769414, 2024). "We speculate that high MUC5AC expression and low MUC5B expression might be biomarkers primarily reflecting smoking exposure and thus associated with the risk of developing emphysema and bronchial wall thickening and with the progression of chronic airflow limitation in the long run." (PMID 39769414, 2024). "Consistent with lung function, subjects who had emphysema on CT scan at follow-up visit had lower MUC5B expression in goblet cells and higher concentration of soluble MUC5AC in the bronchial wash at baseline." (PMID 39769414, 2024). "On the contrary, MUC5B expression in goblet cells was lower in individuals with emphysema at baseline." (PMID 39769414, 2024). "In this study, we assessed the prevalence of the MUC5B minor T allele in patients with ILD and according to ILD subtype, COPD/emphysema, CF/BRECT and PHT who underwent lung transplantation (LTx) at our center between 1991 and 2015." (PMID 35651878, 2022).